BCL2 (BCL2 apoptosis regulator)
Diseases named in the same sentence as BCL2 in open-access papers (continued):
Sharing a sentence is not in itself a finding about the gene and the disease.
infection (continued). "Also, PPE significantly improved the increased jejuna mRNA expression of Bcl-2 due to infection." (PMID 25654088, 2015). "Thus, the finding that Casp2 and Bcl2 interacted during secondary infection suggests that apoptosis is suppressed during secondary infection, in contrast to the induction of apoptosis during primary infection." (PMID 25341656, 2014). "This is a specific effect, since infection with a control adenovirus encoding luciferase (adLuc) did not modify apoptosis and Mcl-1 silencing or overexpression did not modify expression of Bcl-XL or Bcl-2 (data not shown)." (PMID 21977009, 2011). "In addition, gp120/CD4 interactions may promote the activation, expansion and suppressive potential of Treg v effector cells, by up-regulating expression of the anti-apoptotic factor BCL-2, thereby prolonging cell survival and infection." (PMID 20174666, 2010). "Stable expression of Bcl-2, known to have oncogenic properties, may lead to adaptation of the cell, which in turn might affect virus replication and the outcome of infection." (PMID 17904678, 2008). "WB analysis showed that following ME49 infection, AZD1208-treated mice exhibited significantly reduced BCL-2 protein levels and significantly elevated BAX and cleaved-Caspase3 protein levels compared to the control and Pyrimethamine groups." (PMID 41557744, 2026). "Given that E. chaffeensis is known to increase the expression of anti-apoptotic B-cell lymphoma 2 (BCL-2) family members and myeloid cell leukemia 1 (MCL-1) is a transcriptional target of STAT3, we investigated MCL-1 expression during infection." (PMID 41115066, 2025). "By 3 weeks post infection, CD69hi CD49alo and CD69hi CD49ahi TRM dominated, giving way in turn to two Bcl-2-expressing TEM and TRM subsets by 2 months post infection." (PMID 40060443, 2025). "It is noteworthy, though, that the anti‐apoptotic (BCL2)/pro‐apoptotic (BAX) ratio significantly decreased only in SARS‐CoV‐2‐infected HCOs, indicating that after infection, apoptosis is somewhat enhanced in this neural model." (PMID 39950320, 2025). "Studies have shown that LPS infection enhanced the expression of Caspase-3, Caspase-8, Caspase-9, and BAX genes and proteins while reducing the levels of BCL-2 gene expression and protein abundance." (PMID 40136393, 2025). "In GSC cultures, the infection by ZIKV induced miR-34 expression, inhibiting the anti-apoptotic protein Bcl-2 and Numb, the antagonist of Notch, both involved in GSC invasiveness." (PMID 40141375, 2025). "At the same time point, 26544/OG10 infection resulted in increased TLR3 receptor, IRF7 transcription factor, and BCL2 expression." (PMID 40530033, 2025). "HTi pDCs also showed elevated RUBCNL (autophagy),59BCL11A (enhances Bcl-2 and pDC development), and PRXL2A (redox regulation), reinforcing the notion of autophagy activation and mitochondrial stress in response to infection." (PMID 41321641, 2025). "Our data suggest systemic changes in the host during early infection, indicated by the altered expression of PRs, DDX5, BCL2, ANGPTL4, and other regulatory genes during early MDV infection." (PMID 39066292, 2024). "In undernutrition 65% + infection group, PD-1 (P = 0.0231), TCR (P = 0.0075), Bcl-2 (P = 0.0110) and Caspase-3 (P = 0.0475) were all upregulated, and TCR was also upregulated the most." (PMID 38185681, 2024). "In order to characterize the mechanism by which the infection with Pg-LPS or Pg induces IEC-6 cellular apoptosis, the protein expression levels of Bcl-2 and Bax were detected by western blotting." (PMID 38731952, 2024).
infection (continued). "In both in vitro and in vivo experiments, rNDV or rNDV‐TRAIL infection activated BAX production and deactivated Bcl‐2 production, particularly evident in the BAX/Bcl‐2 ratio, which exhibited a more substantial increase in HT‐29 cells compared to HCT116 cells." (PMID 37843231, 2023). "Immunohistochemical results showed that the expression of HSPA5, Ki-67 and BCL2 decreased, and the expression of autophagy marker LC3B decreased and the expression of P62 increased after LV-miR-197-3p infection." (PMID 35342334, 2022). "On the other hand, the expression levels of BCL2, CDKN2A, IL-6, and PPARA remained similar in both male and female mice after infection but were significantly upregulated in male mice after infection in combination with exogenous SP-A2 (1A0) protein." (PMID 35844510, 2022). "A549 cells were collected at 12 h post-infection to detect the expression changes of genes related to LAP, including Bcl-2, Beclin, Rubicon, IFN-γ, and LC3, through Western blotting." (PMID 35159170, 2022). "Consistent with previous reports showing that MDA-7/IL-24 inhibits angiogenesis, induces apoptosis by inhibiting Bcl-2, and promotes ER stress, Ad.5-TCTV infection reduced CD-31 and Bcl-2 levels and increased GRP-78 protein levels in treated tumors." (PMID 33670594, 2021). "The virus, after 48 h of infection, shifts from MCL-1 to Bcl-2 as the primary antiapoptotic tool, and the upregulation of Bcl-2 is mediated by integrin signaling events following initial viral binding." (PMID 33408225, 2021). "Analysis of antigen-specific memory precursors revealed a dose-dependent increase of antigen affinity following Bcl-2 inhibition for both days after ABT-199 injection, though the effect was stronger when it was administered on day 3 after infection." (PMID 32182234, 2020). "When analyzing intracellular Bcl-XL levels in response to infection and AREG stimulation, we observed a similar induction as seen for Bcl-2." (PMID 32082070, 2019). "From 12h to 72h post-infection, compared with the lean group or the DIO group, the expression levels of Caspase-3, Caspase-9 and Bax mRNA, and Bax/Bcl-2 mRNA ratio in the lean-E." (PMID 31085802, 2019). "All pro- (Casp-8, FADD, BAX, and BAK) or anti-apoptotic (BCL-2 and XIAP) genes tested were down regulated at early time points post-SVA infection (2–4 h p.i.)(p < 0.05 when compared to mock-infected cells)." (PMID 30918505, 2019). "In the present study, a significant increase in the Bcl-2 mRNA transcript was encountered in both the HD and UCB groups at 16 h following infection with BCG vaccine." (PMID 31346322, 2019). "Cells infected with JEV, DENV and ZIKV, and treated with either ABT-737 (targeting BCL2, BCLW and BCLXL) or A-1331852 targeting BCLXL exhibited cell death at 3 days-post infection." (PMID 30261081, 2018). "To corroborate these data, we repeated these infection studies and assessed the impact of ExoS/GAP on Bax and Bim (pro-apoptotic), and Bcl-2 and Bcl-XL (anti-apoptotic) proteins in mitochondrial fractions by Western blotting." (PMID 30232373, 2018). "LV-CREB133-GFP infection abolished Tat-HA-NR2B9c’s regulating on CREB activation, and expression of Bcl-2." (PMID 29018405, 2017). "In the present study, after infection with AdC7-SP/E1A-ΔE3, NCI-H508 cells had declining levels of antiapoptotic protein MCL-1 and Bcl-2, whereas Huh7 cells had decreased expression of MCL-1and Bcl-xl." (PMID 28460470, 2017). "After infection, both BCL-2 and pro-Casp3 were up-regulated, while TC had a higher expression of BCL-2 and lower expression of pro-Casp3 than LW pigs." (PMID 28704922, 2017). "Effector T cell populations expanding in response to infection or immunization have been shown to express high levels of CD38 and the proliferation marker Ki67 but low levels of the anti-apoptotic molecule Bcl2." (PMID 27662621, 2016).
infection (continued). "Accordingly, we measured the expression of Ki67 and Bcl2 by flow cytometry within CD38+ and CD38- CD4+ T cells circulating in the healthy volunteers prior to infection, as well as at peak of infection seven days after inoculation." (PMID 27662621, 2016). "Conversely, the expression of the anti-apoptotic marker Bcl2 was significantly reduced in CD38+ CD4+ T cells compared to CD38- CD4+ T cells both prior to and at peak infection (p = 0.002)." (PMID 27662621, 2016). "Parasite challenge during ABT-199 or ABT-263 mediated inhibition of Bcl-2 in both THP-1 MDM and hMDM showed lower infection as compared to vehicle-treated controls (ABT-199, ABT-263)." (PMID 27826299, 2016). "Infection of macrophages with virulent M. tuberculosis decreased Annexin V levels along with a concomitant decrease in AIF levels and an increase in Bcl2 levels." (PMID 26132135, 2015). "Collectively, these results demonstrate that the attenuation of an MHV68 vBcl-2 BH2 mutant virus in transitional B cells can be rescued by host Bcl-2 expression, and accordingly, that the vBcl-2 BH2 mutant is competent for transitional B cell infection." (PMID 24516386, 2014). "In HIV-1LAI.04-infected lymphoid tissues, IL-7 25 ng/mL increased Bcl-2 expression in HIV-1-infected CD4+ T cells on average 2.3±0.1 fold and 2.4±0.1 fold on day 6 and 9 post infection, respectively (n = 8, p<0.0001)." (PMID 23408885, 2013). "For HIV-1BaL-infected lymphoid tissues, IL-7 increased Bcl-2 expression in HIV-1-infected CD4+ T cells 2.2±0.2 fold and 2.6±0.2 fold on day 6 and 9 post infection, respectively (n = 6, p<0.001)." (PMID 23408885, 2013). "When analyzing for BIM in direct relation to Bcl-2, we observed that after 6 days of infection, LCMV-specific CD8 T cells from +/+ mice exhibit an increased BIM to Bcl-2 ratio, as compared to FOXO3−/− CD8 T cells." (PMID 22359505, 2012). "Other EBV factors, including the viral Bcl-2 analogous BALF1 and BHRF1, also play critical roles in B-cell transformation since their very early expression after infection, prevents EBV-infected B cells from undergoing apoptosis." (PMID 23251493, 2012). "We therefore analyzed Ki67/Bcl-2 expression in M38-specific and M45-specific CD8 T cells isolated from lungs or lymph nodes on day 12 post infection and during latency." (PMID 22046127, 2011). "It has been observed that after infection of these cells with NDV, the Bax expression increased whereas Bcl-2 expression decreased." (PMID 21810274, 2011). "In agreement with that, here we have shown that after infection with NDV, there was very little alteration on the mRNA levels of Bax and Bcl-2 from those levels." (PMID 21810274, 2011). "Infection with STAT3-shRNA reduced the mRNA levels of ROR1 and the Stat3-regulated genes STAT3, Bcl2, Bcl-XL, Cyclin D1, c-Myc, WAF1/p21, and Pim1." (PMID 20686606, 2010). "After infection by L. pneumophila ΔflaA, sdhA::kan, cell death levels measured by TUNEL staining were similar in Tg(bcl2) 535rm macrophages and control B6 macrophages." (PMID 19521510, 2009). "For example, iNOS-mutant mice develop significantly more pronounced Th1 responses than wild-type mice upon infection, and IFN-γ-induced NO can downregulate Bcl-2 expression and induce apoptosis of primed T cells 63,64." (PMID 18792404, 2008). "Genes for the Bcl antagonists BCL2-antagonist of cell death, BH3 interacting domain death agonist, BCL-X, and BAK appeared to be induced in the later stages of infection; all of these factors promote apoptosis by inhibiting Bcl-2." (PMID 17725815, 2007). "Collectively, these data demonstrated that in productive infection, pomalidomide increased the expression of Bcl-2 and did not induce apoptosis, contrary to the anticipated effects of the drug." (PMID 39902962, 2025).
infection (continued). "Apoptotic markers (caspase-3, Bax, Bcl-2) were analyzed by immunofluorescence and immune genes expression kinetics (TLR3/7, RIGI, MDA5, IL-1β, IL-6, TNFα, IL-10, IFNβ and β-catenin) were measured at defined time points post-infection by RT-qPCR." (PMID 41157617, 2025). "At 24 h post-infection, qPCR demonstrated marked upregulation of pro-apoptotic Bax mRNA (p < 0.001 vs. PBS control) concomitant with significant downregulation of anti-apoptotic Bcl-2 (p < 0.05), resulting in a reduced Bcl-2/Bax ratio (p < 0.05)." (PMID 41011363, 2025). "Notably, STAT5A is known to promote expression of the anti-apoptotic gene BCL2, which was also present among the filtered KEGG gene list, suggesting a potential mechanism for increased cell survival during infection." (PMID 41356367, 2025). "Currently, it remains unknown which pro-survival genes impact cell death induction during infection with reovirus, TNF, or Bcl2 inhibitor treatment." (PMID 41042063, 2025). "After LvLL knockdown, the expression levels of Bcl-2 in the dsLvLL + WSSV group were approximately 0.46-fold (p < 0.05), 0.20-fold (p < 0.01), and 0.05-fold (p < 0.01) that of the dsGFP + WSSV group at 24, 36, and 48 h after WSSV infection, respectively." (PMID 39452067, 2024). "However, at the 8th week post-infection, PD-1 (P = 0.0420), PD-L1 (P = 0.0406), TCR (P = 0.0423), Bcl-2 (P = 0.0178), Caspase-3 (P = 0.0349) and TLR4 (P = 0.0449) were upregulated in undernutrition 75% + infection group." (PMID 38185681, 2024). "Our current research excludes the lungs, where we do not observe changes in miR-16b and Bcl-2 expression during L. europaeus GI.1 and GI.2 genotype infection." (PMID 38516020, 2024). "We also cannot rule out that phosphorylation of BCL2 promotes infection resistance by impacting cellular functions other than canonical autophagy." (PMID 39602254, 2024). "However, infection markedly increased the expression of inflammatory cytokines (IL-6 and TNF-α) and the apoptotic genes (Caspase-3 and BCL2)." (PMID 36875142, 2023). "Also consistent with reduced Bcl2 expression, increased proportions of dead Malat1scr/scr cells were observed in both the KLRG1+ and KLRG1− cell fractions at day 7 during LM-GP33 infection." (PMID 38127070, 2023). "The inflammatory response of the body after infection requires the initiation of the NF-κB signaling pathway, and the inflammatory factors TNF-α and IL-1β activate NF-κB, which regulates the production of the Bcl-2 anti-apoptotic protein." (PMID 37570890, 2023). "do not lead to dysregulation of the Bax/Bcl-2 ratio, and in long-term infection, they even inhibit apoptosis of host renal cells." (PMID 38041167, 2023). "Under normoxia, the infection resulted in down-regulation of Bcl-2 and up-regulation of Bax regardless of the genotype of the pathogen." (PMID 35755850, 2022). "SARS-CoV-2 is projected to downregulate BCL-2 anti-apoptotic proteins, so a BCL-2 inhibitor could exacerbate cellular damage during infection." (PMID 36569952, 2022). "In agreement with the increased level of p-BCL-2 observed as a consequence of H37Rv infection, we did not observe processed caspases-9 and -3, suggesting a suppression or delay of the mitochondrial apoptotic pathway under the evaluated conditions." (PMID 35631013, 2022). "Second, HIV production is, on the whole, higher in BCL2+ CD4 T cells than in BCL2- T cells despite a similar infection frequency, suggesting but not proving the possibility that BCL2 expression favors survival of reactivated, virus producing cells." (PMID 33075109, 2020). "Notably, BCL-2 and its family genes (BCL-XL, BCL-W, and MCL-1) were upregulated during infection with gamma-irradiated M. tuberculosis infection in BMDMs from WT mice but not in those from NEK6-deficient mice." (PMID 32487755, 2020). "As expected, the STAT2−/− hamsters exhibited impairment in the Type 1 IFN response, shown by a lack of change in the expression of bcl-2 and absence of iNOS and IP-10 induction upon infection." (PMID 32704046, 2020).
infection (continued). "The results suggested that Bcl-2 did not effectively suppress JEV-induced cell death during the late period of infection." (PMID 31658698, 2019). "In contrast, in the media neither Bax nor Bcl2 expression changed one week post-infection, and this absence of apoptosis paralleled the lack of reduction in the senescence marker p21 in the media." (PMID 31186381, 2019). "The increase in Bcl-2 occurs largely in response to the up-regulation of pro-apoptotic Bax following infection, which can be inactivated by Bcl-2, but not Mcl-1." (PMID 30274264, 2018). "The increases in LC3BII/I ratios were not reduced by Ad∆∆-infection and the virus did not attenuate mitoxantrone-induced autophagy in the Bcl-2 knockdown PC3 cells." (PMID 29362360, 2018). "The Ad-HRD1 infection significantly suppressed BAX and restored Bcl-2 expression." (PMID 29233968, 2017). "The inability of wortmannin and LY294002, the PI3K inhibitors to prevent the increase in Bcl-2 post infection ruled out the involvement of the PI3K pathway in Bcl-2 changes." (PMID 27826299, 2016). "Importantly, infection-induced STAT-3 phosphorylation and Bcl-2 increase declined when cells were challenged with parasites in IL-13R downregulated conditions or in the presence of AG490." (PMID 27826299, 2016). "While the mechanisms of Leishmania infection have been widely explored, there is no information on how host Bcl-2 behaves during infection with this parasitic protozoan." (PMID 27826299, 2016). "The translocation of Bax into the mitochondria was detected at 4 h during EPEC infection, but not during ΔespC mutant infection, perfectly correlating with the Bcl-2 data." (PMID 27329750, 2016). "This enabled us to focus primarily on the impact that decreased myeloid cell death had on infection, and not on homeostatic effects of constitutive bcl-2 expression." (PMID 27973535, 2016). "On the contrary, the peritoneal macrophages isolated from TLR-2 knockout mice of the same strain showed no significant increase in Bcl-2 levels post infection." (PMID 27826299, 2016). "The wild-type infection-generated decrease in Bcl-2 protein band intensity was recorded as 40% in comparison to infection with the ΔespC mutant or the negative control and cells infected with the ΔescN mutant." (PMID 27329750, 2016). "Macrophages knocked down for either Bcl-2 or Mcl-1 showed no significant impact on viability upto 48 h of infection." (PMID 27826299, 2016). "Here, nuclear translocation of Bcl-2 and p-AKT increased after rAd-ASPP2 infection for 48 hours." (PMID 25980493, 2015). "In human gingival fibroblasts with inflammation activation of bcl2 has not been observed in different stages of the infection and giant-cell epulis." (PMID 26251029, 2015). "At 96 hours after infection, VEGF and BCL-2 protein levels were identical between the two groups." (PMID 25961846, 2015). "Analysis of Casp2 protein interactions revealed that it interacted with Bcl2 during secondary but not primary infection." (PMID 25341656, 2014). "Infection with 0.0001 MOI downregulated bcl-2 in non-irradiated cells but was upregulated by 27% after irradiation when compared to non-irradiated infected cells (P = 0.05)." (PMID 25005804, 2014). "The expression of the antiapoptotic gene, Bcl-2, was significantly decreased and the IL-24 receptor was markedly expressed in Hep-2 cells following infection with Ad-hIL-24, but not in HUVECs." (PMID 24527085, 2014). "VEGF and GCS showed Nrf2-dependence at 8 hr p.i. but seemed to be independent of Nrf2 activity at 24 hr p.i., while Bcl-2 steadily increased during the course of infection in an entirely Nrf2-dependent manner." (PMID 25340789, 2014). "The expression of Bcl-2 was significantly decreased while the IL-24 receptor was markedly expressed in Hep-2 cells following infection with Ad-hIL-24, but not in HUVECs." (PMID 24527085, 2014). "After treatment with CPX for 24 hr, ∼35% of cells stained positive for Bcl-2, irrespective of infection." (PMID 24086341, 2013).